PNPLA5 (patatin like domain 5, triacylglycerol lipase )
Description:
Has abundant triacylglycerol lipase activity.
Synonyms: GS2L; dJ388M5.4; dJ388M5
Tractability: No criterion of Open Targets' tractability assessment is met for any kind of drug.
Gene: Protein-coding gene on chromosome 22 (43,878,568 to 43,892,494, reverse strand). Ensembl gene ENSG00000100341.
Subcellular location (Human Protein Atlas): Annulus; Mid piece
Pathways (Reactome):
Metabolism: Triglyceride catabolism
Gene Ontology:
Molecular function: protein binding; triacylglycerol lipase activity; hydrolase activity
Biological process: lipid homeostasis; triglyceride catabolic process; lipid catabolic process; lipid metabolic process
Cellular component: cytosol; lipid droplet; membrane
Genetic constraint (gnomAD): Loss-of-function variants: 45 observed, 44.97 expected, observed/expected ratio (o/e) 1, 90% interval 0.79 to 1.28. The upper end of that interval is the gene's LOEUF score, 1.28, which puts it in group 5 of 6, group 1 being the genes least tolerant of losing a copy. Missense variants: 603 observed, 533.58 expected, observed/expected ratio (o/e) 1.13, 90% interval 1.06 to 1.21. Synonymous variants: 243 observed, 229.89 expected, observed/expected ratio (o/e) 1.06, 90% interval 0.95 to 1.18.
Homologues: Orthologues: chimpanzee PNPLA5 (98% identical), macaque PNPLA5 (91% identical), dog PNPLA5 (74% identical), rat Pnpla5 (70% identical), mouse Pnpla5 (66% identical), guinea pig PNPLA5 (64% identical). Paralogues in human: PNPLA2 (36% identical), PNPLA3 (35% identical), PNPLA1 (28% identical), PNPLA4 (17% identical).
Diseases named in the same sentence as PNPLA5 in open-access papers:
PNPLA5 is named in the same sentence as 6 diseases in open-access papers, as found by Europe PMC text mining. Sharing a sentence is not in itself a finding about the gene and the disease. The quoted sentences say what the papers report.
Obesity (2 papers, 2009 to 2013). Accumulation of substantial excess body fat. "One group of genes (SERPINA12, CPE, SERPINA11, MTCH2, PNPLA5, INTS1, APOM) was associated (cosine value >0.1) with obesity and diabetes." (PMID 23544116, 2013). "No variants in the PNPLA2, PNPLA4 and PNPLA5 were associated with obesity in this cohort." (PMID 19390624, 2009).
Lipid metabolism disorders (1 paper, 2022). "Lipid metabolism disorders, abnormal bleeding, and reduced male fertility induced by Pnpla5 deletion have been reported." (PMID 35962316, 2022).
bacterial infections (1 paper, 2022). "Therefore, it is reasonable to assume that Pnpla5-/- rats may also suffer from recurrent bacterial infections." (PMID 35962316, 2022).
tumor (1 paper, 2023). "BRAF (Z-score=5.546, p<0.001) and PNPLA5 (Z-score=5.546, p<0.001), a gene closely associated with lipid metabolism, were the only two genes implicated in tumor pathogenesis." (PMID 37795451, 2023).
PNPLA5 also shares sentences with these, for which no sentence is quoted: diabetes (1 paper); familial hypercholesterolemia (1).